EGFR (epidermal growth factor receptor)
Diseases named in the same sentence as EGFR in open-access papers (continued):
Sharing a sentence is not in itself a finding about the gene and the disease.
tumor (continued). "Amivantamab is a BsAb targeting EGFR and MET, which can bind to both EGFR and c-MET sites outside of tumor cells and also kill tumor cells through mechanisms such as Fc-mediated antibody-dependent cell-mediated cytotoxicity (ADCC) effect." (PMID 41000392, 2025). "Overexpression of EGFR is common in NSCLC; therefore, liposomes modified with cetuximab can specifically target tumor cells and improve the delivery efficiency of siRNA." (PMID 39940962, 2025). "Principal component analysis (PCA) illustrated that agrin–EGFR expression along with other YAP/TAZ targets, aligned together in lung tumors distinct from the normal or tumor‐adjacent tissues." (PMID 40165020, 2025). "In a previous study involving mouse models and human samples, proteins produced by CAFs from tumor tissues, such as kynurenine, activated the downstream AKT and extracellular signal-regulated kinase (ERK) pathways, contributing to EGFR-TKI resistance." (PMID 40002883, 2025). "Anti-EGFR CL4 and anti-PDGFRβ RNA aptamers were selected for tumor and stromal cells targeting, respectively." (PMID 39940134, 2025). "In PLC/PRF/5 tumor‐bearing mice and PDTX mouse models, ZAK‐I‐57 treatment (30 mg/kg) resulted in substantial downregulation of EGFR, c‐Myc, and Bcl‐2, with a concurrent increase in Bax expression." (PMID 40727254, 2025). "Gains of chromosome 7 (involving EGFR) and losses of chromosome 10 (involving PTEN) are hallmarks of GBM, leading to enhanced tumor cell proliferation, survival, and invasion, ultimately contributing to the rapid growth and poor prognosis of GBM." (PMID 39936963, 2025). "ecDNA amplifications that harbor driver oncogenes such as EGFR, MYC, MDM2, and CDK4 were detected in 17.1% of 39 human tumor subtypes, including GBM24." (PMID 40678238, 2025). "A clinical study, using single-cell RNA sequencing of biopsy specimens from EGFR-mutant NSCLC, showed that macrophage infiltration decreased with EGFR-TKI treatment, to which the tumor was sensitive and increased in resistant cases." (PMID 40002883, 2025). "The reverse transcription real-time PCR assay revealed higher expression of tumor markers CDKN2A, EGFR, and PDGFRL in monophasic SS compared to biphasic tumors." (PMID 41155410, 2025). "In fact, the expression levels of EGFR, MYC, CDK4, and MDM2 genes commonly carried by ecDNA rank in the top 1% of tumor genomes." (PMID 41030947, 2025). "Its therapeutic benefits in reversing immune escape and overcoming epidermal growth factor receptor-tyrosine kinase inhibitor (EGFR-TKI) resistance have been validated, with ongoing research elucidating its anti-tumor mechanisms." (PMID 41322146, 2025). "Our Protein–protein interaction (PPI) network analysis results demonstrated that the key target genes of FSH for anti-tumor treatment were AKT1, EGFR, BCL2, CTNNB1 and HSP90AA1." (PMID 40230723, 2025). "Decorin also destabilizes E‐cadherin via EGFR/ERK signaling, suppressing tumor cell invasion and metastasis." (PMID 40542654, 2025). "In cancer, ANO1 regulates key signaling pathways, including EGFR, MAPK/ERK, and PI3K/Akt, driving tumor growth and metastasis." (PMID 40356890, 2025). "Another trial (NCT04153799) using CXCR5-modified EGFR-CAR-Ts achieved two partial responses and five long-lasting stable diseases among 11 patients, suggesting enhanced tumor trafficking." (PMID 40904467, 2025).
tumor (continued). "We investigated entinostat effects on EGFR and amphiregulin (AREG) expression in various cell line- and primary patient tumor-based in vitro, ex vivo and in vivo models, on the mRNA and protein level." (PMID 39864337, 2025). "It should be mentioned, however, that we found EGFR downregulation in one cell line (NCI-N87) as well, suggesting some heterogeneity even within a given tumor entity." (PMID 39864337, 2025). "Our study engineered four EGFR/B7H3 bsAbs with differential binding affinities, all of which demonstrated superior tumor cell binding, EGFR pathway inhibition, and ADCC activity compared to cetuximab." (PMID 41291854, 2025). "For instance, MCLA-158 (petosemtamab), a BsAb targeting both EGFR and LGR5, exhibited strong growth inhibition of patient-derived CRC organoids and orthotopic xenograft tumor models, including KRAS mutant CRCs resistant to cetuximab." (PMID 40076613, 2025). "In EGFR-overexpressing A549 cells, NIR irradiation triggered hyperthermia for tumor ablation while releasing curcumin to eliminate residual cancer cells." (PMID 39940134, 2025). "These CAFs facilitated tumor EMT and enhanced tumor invasion by secreting an abundance of extracellular matrix proteins, ultimately leading to EGFR-TKI resistance." (PMID 40003951, 2025). "This is in contrast with its significant impact on EGFR signaling, 18F-FDG uptake, and anti-tumor responses in an intracranial model of EGFR kinase mutant NSCLC, its approved clinical indication." (PMID 40051661, 2025). "We demonstrated that DTIC therapy followed by infusion of murine CAR T cells targeting the human/murine hybrid EGFR (EGFR mCAR T cells) provided superior tumor control and prolonged survival compared to monotherapy with either DTIC or EGFR mCAR T cells alone." (PMID 41516067, 2025). "A prominent example is cetuximab (IgG1), which binds to the epidermal growth factor receptor (EGFR), thereby interrupting intracellular signaling pathways and inhibiting tumor cell proliferation." (PMID 40649964, 2025). "Owing to ongoing tumor progression and significantly elevated NSE levels, we performed a lung biopsy 6 months post resistance to EGFR-TKI therapy, which confirmed a diagnosis of LCNEC." (PMID 40040728, 2025). "9c had the capability to decrease the protein levels of the EGFR, p-AKT, P-ERK and NSA2 in tumor tissue from NCI-H358 xenografts." (PMID 40076615, 2025). "Of these, one of the most common is cetuximab, an epidermal growth factor receptor (EGFR) inhibitor that prevents tumor cell proliferation, promotes complement mediated cell lysis, and allows for tumor death via antibody-dependent cell-mediated cytotoxicity." (PMID 40547025, 2025). "Circulating tumor cells (CTCs) were detected through the expression of epithelial markers (EPCAM, EGFR, and MET)." (PMID 40616388, 2025). "TAVO412 demonstrated anti-tumor activities against four NSCLC xenograft models with low, moderate, and high levels of wild-type genotype EGFR expression." (PMID 40452841, 2025). "Although third-generation EGFR-TKIs, such as Furmonertinib, have improved outcomes for patients with EGFR-mutant LUAD, drug resistance and tumor adaptation remain major challenges." (PMID 41307822, 2025). "EGFR, ALK, and Kirsten rat sarcoma (KRAS) drive tumor progression by increasing cell survival and proliferation in bone metastasis." (PMID 41245887, 2025). "Moreover, given the EGFR contribution to the immunosuppressive environment, clinical EGFR inhibitor could improve chemo-therapeutics treatments of tumors, reducing Treg activity and improving the anti-tumor immune response." (PMID 39966897, 2025). "PTEN targets the PAFR signaling, which interacts with EGFR and its downstream cascades, and PAFR/EGFR blockade has been shown to inhibit the growth of tumor cells." (PMID 40160442, 2025). "Firstly, it activates the EGFR/FAK signaling pathway, leading to increased tumor proliferation, apoptosis inhibition, and enhanced migratory invasiveness." (PMID 41383589, 2025).
tumor (continued). "CHIs combined with EGFR-TKIs improved the expression of CD3+ and CD4+ T cells, as well as the CD4+/CD8+ ratio, implying that CHIs exert their anti-tumor activity by augmenting human immune function." (PMID 41347160, 2025). "For EGFR- and EpCAM-positive HCT116 cells, a 100-fold increased cell killing activity was detected compared to EGFR-positive or EpCAM-positive tumor cells." (PMID 40936895, 2025). "Consistent with this concept, recent work has demonstrated metabolism-directed strategies to overcome EGFR-TKI resistance, including inhibition of BCAT1/BCAA metabolism and disruption of kynurenine–AHR signaling in the tumor microenvironment." (PMID 41142757, 2025). "Conversely, mSWI/SNF derived subunit SMARCB1 was detected to suppress tumor growth and enhance the oncological therapeutic response in in vivo studies by inducing epigenetic modifications in the GLI-1 and EGFR genetic sequences." (PMID 39971779, 2025). "In the EGFR-overexpressing SW480 cells, the targeted system showed enhanced uptake and significant anti-tumor effects." (PMID 39940134, 2025). "Targeting CSC-specific markers such as EGFR and CD44 has moderate efficacy in controlling tumor size and the progression of cancer." (PMID 40678631, 2025). "In EGFR-mutant NSCLC, M2-like macrophages support tumor progression, increasing in TKI-resistant tumors." (PMID 40002883, 2025). "Hence, subsequent EGFR‐TKI treatment could still exert an anti‐tumor effect in such cases." (PMID 39741120, 2025). "Early positive results were seen in a HNSCC patient whose EGFR and MET expressing tumor was transplanted into humanized patient-derived xenograft models and exposed to Pembrolizumab with Amivantamab." (PMID 40868227, 2025). "In HA-rich RKO tumors, intravenous administration of EGFR × HYAL effectively inhibited tumor growth, achieving a tumor growth inhibition (TGI) of 58% compared to 37% for EGFR × Null, without affecting the mice’s body weight." (PMID 41228205, 2025). "EGFR and TROP2 emerged as broadly expressed and therapeutically actionable targets, while TF and EpCAM showed potential in specific tumor contexts." (PMID 40806559, 2025). "We further explored how expression levels of EGFR, EpCAM, TF, and TROP2 varied with clinical parameters such as tumor stage, grade, age, HER2 expression, and Ki-67 proliferation index." (PMID 40806559, 2025). "Click chemistry using a fluorobenzylazide label, as in our study, was used to produce the labeled aptamer [18F]FB-ME07, which was tested in xenograft tumor models of A431, U87MG, and HCT-116 with different levels of EGFR expression." (PMID 41473440, 2025). "Early-phase trials targeting EGFR, MSLN (mesothelin), PSCA (prostate stem cell antigen), and MUC1 have shown preliminary evidence of tumor control, albeit with challenges related to trafficking and the immunosuppressive tumor microenvironment." (PMID 41303058, 2025). "The remarkable improvements in tumor response, PFS, and OS shown with cetuximab and panitumumab have raised the possibility of preserving EGFR antibodies for left-sided RAS/BRAF WT tumors." (PMID 41458799, 2025). "Following three different strategies to inhibit mutant‐specific EGFR, the tumor immune microenvironment is at least transiently converted to a more active state, providing a window of opportunity where there may be heightened sensitivity to therapies that promote immune responses against the tumor." (PMID 40859900, 2025). "Lapatinib inhibits the activation of these pathways by targeting EGFR and HER2, thereby blocking cell cycle progression and inducing apoptosis in tumor cells." (PMID 40040723, 2025). "Mechanistically, our results indicate that the enhanced anti-tumor effects observed with gefitinib + G31P treatment are primarily due to inhibition of PI3K/AKT and MAPK/ERK pathways, which are central to EGFR-driven tumor growth." (PMID 41425704, 2025).
tumor (continued). "EGFR expression is notably upregulated in CRC tissues and, upon binding to EGF, activates intracellular signaling cascades involved in tumor cell polarization, proliferation, and autophagy." (PMID 40060193, 2025). "Erlotinib, a food and drug administration (FDA)-approved EGFR kinase inhibitor for treating EGFR-mutant NSCLC, can reduce CIP2A levels, which indirectly restores the tumor-suppressive activity of PP2A." (PMID 41155727, 2025). "For example, AKT1 participated in seven biological processes, EGFR and STAT3 were involved in six, and SRC contributed to five biological processes, highlighting their essential roles in mediating the anti-tumor effects of steamed PJR." (PMID 41465428, 2025). "The results demonstrated an enhancement in NK killing capacities for both EGFR-expressing (HeLa) and HER2-expressing (SK-BR-3) cells, indicating the significance of the natural NKp30/B7-H6 axis in tumor recognition by the immune system." (PMID 39811682, 2025). "We found that tumor-derived EGFR+ Epi exhibited pronounced CNV signals across multiple chromosomes and were significantly enriched in tumor samples compared to normal controls." (PMID 40948762, 2025). "The EGFR/PI3K/AKT/mTOR pathway is intricately involved in cell proliferation, survival, and tumor metastasis." (PMID 40699663, 2025). "EGFR is a key regulator of cell proliferation and survival, while TNF plays a dual role in promoting inflammation and remodeling of the tumor microenvironment." (PMID 41281432, 2025). "Genetic knock-in of EGFR-E804K in cells reduces the level of GTP-bound Rheb, and significantly suppresses mTORC1 activation, cell proliferation and tumor growth." (PMID 40259053, 2025). "The inhibitory effect on tumor growth is further enhanced by co-inhibition of FGFR, EGFR, and MET, which reduces activation of ERK and Akt." (PMID 41516252, 2025). "This enhanced tumor accumulation, controlled release, and degradation of targets like cyclin D1 or BRD4 in EGFR- or HER2-positive models, achieving high biosafety and antitumor efficacy." (PMID 41304914, 2025). "When we collected the tumors and examined the levels of protein expression, we found that SORL1 knockdown led to the downregulation of both EGFR and FGFR4 in the tumor samples." (PMID 39858026, 2025). "Once inside the tumor, OV-Cmab-CCL5 not only disrupted EGFR signaling, which is often upregulated in GBM, but also triggered a strong immune response." (PMID 40867316, 2025). "Tumor cells have specific tumor markers on their surface and, according to the WHO classification, one of the key markers of GB cells is Epidermal Growth Factor Receptor (EGFR)." (PMID 40943631, 2025). "After the development of resistance to EGFR-TKI treatment, tumor cells undergo significant alterations in their gene expression profiles." (PMID 40003951, 2025). "Mice fed the EGFR inhibitor Gefitinib reduced tumor burden by 88% in Tpl2−/− mice, while the HER2 inhibitor Lapatinib achieved a 50% tumor reduction." (PMID 41154417, 2025). "As an irreversible EGFR inhibitor, OSI blocks kinase activity by binding to the Cys-797 residue of EGFR, and its effects diminish only upon tumor cell-mediated EGFR receptor resynthesis." (PMID 40871064, 2025). "For example, some drugs have been designed to simultaneously inhibit EGFR and ALK, two mutant kinases commonly found in NSCLC, as a way to overcome the resistance of tumor cells to single-target EGFR inhibitors." (PMID 40240755, 2025). "EGFR and VEGFR signaling pathways enhance tumour development and angiogenesis via substantial autocrine and paracrine interaction." (PMID 41145684, 2025). "As a tumor suppressor, ERRFI1 directly interacts with EGFR to inhibit its activation, thereby suppressing tumor cell proliferation and metastasis." (PMID 40308576, 2025).
tumor (continued). "Their findings suggest that SII is notably related to prognosis in EGFR-mutant lung ADC patients receiving first-line EGFR-TKIs, with higher SII indicating greater tumor burden, more profound immunosuppression, and poorer outcomes." (PMID 41268168, 2025). "Specifically, it inhibits proliferation, adhesion, invasion, and metastasis in various tumor cells by modulating signaling pathways such as JNK, HIF-1α, PI3K/Akt, Nrf2, Wnt, JAK2-STAT3, and EGFR." (PMID 41156537, 2025). "Following transscleral tumor therapy and EGFR-TKI therapy, the patient achieved a best corrected visual acuity (BCVA) of 20/20 in both eyes with controlled tumor progression, surviving with stable disease for 3 years." (PMID 41140667, 2025). "Last, we evaluated the therapeutic effects of individual or combination therapy with the KAT7 inhibitor WM-3835 and the EGFR inhibitor Erlotinib on orthotopic GSC11 and GBM6 tumor xenograft models." (PMID 40678238, 2025). "The improved efficacy of Gel@Cmab/PCZ is due to the enhanced delivery of both cetuximab and PCZ to the tumor site, which contributes to enhanced ADCC activity and inhibition of the EGFR downstream pathway." (PMID 39560161, 2025). "We suggest that combining EGFR-TKI at the early stage of radiotherapy might not only produce a longer-term effect that is beneficial to the enhancement of the radiotherapy outcome but also inhibit tumor recurrence due to radiation-induced stemness-responsive cells." (PMID 40003899, 2025). "For example, EGFR overexpression upregulates key markers of M2 macrophages, including STAT6, CD163, and MRC1, which negatively affects tumor-infiltrating lymphocytes and promotes resistance to cetuximab, an EGFR-specific antibody." (PMID 40486875, 2025). "EGFR is a tumor-associated antigen that is also expressed in normal tissue, although at a substantially lower level; therefore, evaluating the on-target, off-tumor (OTOT) toxicity associated with 7D12-T cell therapy is imperative, especially for hIL21-armed 7D12-T cells." (PMID 40722671, 2025). "Overexpression of SPRY2 abolishes the inhibitory effect of co-inhibition of FGFR, EGFR, and MET on tumor growth despite reduced ERK and Akt activation, suggesting that additional mechanisms are involved in the tumorigenic potential of SPRY2 in GB." (PMID 41516252, 2025). "Most significantly, WntSI effectively overcame acquired resistance to EGFR‐TKIs resulting from MET amplification in both cell line‐derived and patient‐derived tumor xenograft mouse models, while exhibiting exceptional safety measures." (PMID 38867713, 2024). "The tumor subcluster expressing high levels of both EGFR and MET (EMHIGH) was define and analyzed for top 50 genes to identify differentially expressed genes (DEGs) in EGFRHIGH/METHIGH and EGFRLOW/METLOW tumor subclusters." (PMID 38916448, 2024). "In vivo, we also observed a significant reversal of increased tumor growth and cervical LN metastasis in ADAMTS1-overexpressed HSC-3 cells when these cells were engineered to express shRNA targeting L1CAM or EGFR." (PMID 38263290, 2024). "Extensively studied predictors of tumor immunotherapy include PD-L1, TMB, microsatellite instability (MSI), EGFR, and tumor-infiltrating lymphocytes (TILs)." (PMID 38756661, 2024). "Mechanistically, when c-MET is amplified or overexpressed, it can bypass EGFR pathway inhibition through the ERBB3 receptor-mediated PI3K/AKT and Grb2/MAPK pathways, thereby maintaining tumor cell growth and survival." (PMID 39201787, 2024). "We next evaluated the levels of p-ERK, p-AKTT308, p-AKTS473, p-EGFR, p-HER2, p-IGF1R, p-PDGFR, p-VEGFR and p-FGFR in tumor tissues." (PMID 38795180, 2024). "Abnormal activation of receptor tyrosine kinases (RTKs), such as EGFR, VEGFR2/3, and PDGFR-β, is also involved in the dysregulation of MEK-ERK signaling, leading to tumor progression." (PMID 39518973, 2024). "It inhibits EGFR, HER2, and HER4 phosphorylation, resulting in tumor growth inhibition and regression." (PMID 38680990, 2024).